LINC01561 (long independently transcribed non-coding RNA 1561)
Synonyms: C10orf85; FLJ37402; Em:AC023282.2
Gene: Long non-coding RNA gene on chromosome 10 (120,597,949 to 120,600,124, forward strand). Ensembl gene ENSG00000177234.
Diseases named in the same sentence as LINC01561 in open-access papers:
LINC01561 is named in the same sentence as 5 diseases in open-access papers, as found by Europe PMC text mining. Sharing a sentence is not in itself a finding about the gene and the disease. The quoted sentences say what the papers report.
glioma (1 paper, 2023). A benign or malignant brain and spinal cord tumor that arises from glial cells (astrocytes, oligodendrocytes, ependymal cells). "To know the role of LINC01561 on glioma, we further conducted the effects of the increased level of LINC01561 in glioma cell lines (U251 and U87-MG) in in vitro experiments." (PMID 37114036, 2023). "Transwell experiments revealed that silencing LINC01561 inhibits glioma cell invasion, indicating that downregulation of LINC01561 significantly hindered glioma progression." (PMID 37114036, 2023). "Moreover, LINC01561 was involved in regulating the immune microenvironment of gliomas, which plays a crucial role in tumor initiation and prognosis." (PMID 37114036, 2023). "GSVA results also indicated that LINC01561 may be involved in regulating the prognosis of gliomas." (PMID 37114036, 2023). "However, no reports have shown the involvement of LINC01561 in glioma and its underlying mechanisms remain unknown." (PMID 37114036, 2023). "However, to date, no reports have investigated the involvement of LINC01561 in glioma and its underlying mechanisms remain unknown." (PMID 37114036, 2023). "LINC01561 has been reported in other cancers, but its effect on glioma has not been reported." (PMID 37114036, 2023).
tumor (1 paper, 2023). "The expression of LINC01561 in the tumor samples is higher than that in the normal samples, but significant differences were found only in the LGG samples." (PMID 37114036, 2023).
LINC01561 also shares sentences with these, for which no sentence is quoted: breast carcinoma (1 paper); cancer (1); non-small cell lung carcinoma (1).